IL6 (interleukin 6)
Diseases named in the same sentence as IL6 in open-access papers (continued):
Sharing a sentence is not in itself a finding about the gene and the disease.
COVID-19 (continued). "The inverse relationship between serum [Na+] and IL-6 was confirmed in a subsequent study that collected data from 380 patients hospitalized at the Careggi University Hospital in Florence, Italy, as well as in a Swiss study that included 184 COVID-19 patients." (PMID 39196447, 2024). "Attenuating the NLRP3 inflammasome pathway by VitD3 was accompanied by a decrease in IL-1β, IL-6, IL-17, and D-dimer, reduced hyperinflammation of severely infected COVID-19 patients, as well as correlated with enhanced type I IFN signaling and reduced disease severity." (PMID 38748756, 2024). "Anti-IL-6 (tocilizumab) improves HRQoL at 6 months in COVID-19 survivors admitted to intensive care, although whether this benefit applies to patients outside of intensive care is unknown." (PMID 39351379, 2024). "Similar to these findings the present study supports the assumption that IL-6 may be a significant predictive biomarker for ICU admission or death in patients with COVID-19." (PMID 38336628, 2024). "Therefore, we believe that examination of LDH, IL-6 and lymphocyte count is a valuable method and should be performed for each patient diagnosed with COVID-19 together with determination of the presence of comorbidities." (PMID 38982355, 2024). "Higher plasma IL-6 and TNFα levels may trigger platelet activation and coagulation, and in turn aggravate thrombosis and hypercoagulation in severe COVID-19 patients." (PMID 38709269, 2024). "Another analyte that received interest early in the pandemic was IL6, as early studies suggested that elevated IL6 in patients with COVID-19 could predict survival outcomes and intensive care unit admission." (PMID 39852788, 2024). "This study outcome closely mirror the findings of the WHO REACT group, indicating that the use of IL-6 antagonists such as Tocilizumab and Sarilumab in COVID-19 patients may reduce 28-day mortality, with an OR of 0.86 and a 95% CI of 0.79–0.95 (p=0.003)." (PMID 39633779, 2024). "In addition to corticosteroid therapy, seven patients received COVID-19-specific treatment: six received anti-IL6 monoclonal antibodies (tocilizumab) and one patient received sotrovimab." (PMID 38993755, 2024). "In critical COVID-19 patients, it is vital to restrict the lethal effect of this particular IL-6." (PMID 37742314, 2024). "Additionally, in comparison to other biomarkers IL-6 was found to be a significant independent predictor regarding both endpoints in the present study, which emphasizes the high predictive value of IL-6 in COVID-19 patients." (PMID 38336628, 2024). "This study aimed to assess a potential organ protective effect of volatile sedation in a scenario of severe inflammation with an early cytokine storm (in particular IL-6 elevation) in patients suffering from COVID-19-related lung injury with invasive mechanical ventilation and sedation." (PMID 38536545, 2024). "Therefore, research indicated that individuals with certain genetic variations in the IL6 gene, like the GG genotype of rs1800795, tended to have higher IL-6 levels and were more likely to experience severe COVID-19 or increased mortality." (PMID 39518964, 2024). "IL-6 based COVID-19 severity score to predict the need for HFNC." (PMID 38394183, 2024). "Moreover, a lot of evidence accumulated suggesting that IL6 is the most predictor cytokine in relation to COVID-19 severity and mortality." (PMID 39346556, 2024). "In this study, we found a significant correlation between the increase in serum IL-6 levels and the increase in procalcitonin levels which indicates severe inflammation due to COVID-19 infection and confirms the importance of monitoring IL-6 levels during COVID-19 treatment." (PMID 38378528, 2024). "IL-6 peaks are temporary in CAR-T patients, particularly if therapy is in place, but IL-6 levels persist in COVID-19 patients for an extended period of time.IL-6 clinical cut-off values that are recommended in this context are beginning to appear, despite the small sample size." (PMID 39458339, 2024).
COVID-19 (continued). "In CRRs with significantly elevated IL-6 (up to a 40-fold increase), IL-6 plays a central role in the resulting inflammatory storm of severe hypersensitivity reactions, autoimmune diseases, and infections like COVID-19." (PMID 39881879, 2024). "Similarly, increased inflammatory mediators including IL-6, IL-8, and TNF-ɑ have been associated with elevated plasma concentrations of syndecan-1, hyaluronan, and HS in severe COVID-19." (PMID 38753622, 2024). "The study concluded that patients with SLD and elevated serum IL-6 levels were at higher risk of experiencing severe illness from COVID-19, highlighting the connection between the inflammatory profile of SLD and the severity of COVID-19 clinical presentation." (PMID 38731216, 2024). "Serum IL-6 was consistently found to be elevated in severe COVID-19." (PMID 38791005, 2024). "However, in this study, we determined the molecular structure and receptors of IL-6 and TNFα alongside the function of pro-inflammatory cytokines TNFα and IL-6 involved in the pathogenesis of COVID-19." (PMID 39118801, 2024). "In addition, their synergistic use in vivo also inhibited the elevation of pro-inflammatory cytokines, including IL-6 and TNF-α—the primary cytokines in the development of acute respiratory distress syndrome (the main cause of COVID-19 deaths)." (PMID 38383655, 2024). "However, the IL-6 level in the ACLF+COVID-19 group was significantly higher than that in the ACLF group (161.43 [82.75 - 479.9] vs 43.47 [14.35-100.21]; p=0.026)." (PMID 39867341, 2024). "In the COVID-19 context, sodium levels were found to be inversely correlated with the pro-inflammatory cytokine IL-6 and positively correlated with the PaO2/FiO2 ratio, suggesting that hyponatremic patients with COVID-19 exhibited increased inflammation and reduced ventilator capacity." (PMID 39335510, 2024). "Both IL-6 and LDH are independent predictive laboratory values for assessing COVID-19 severity, and early declines may be associated with better outcomes." (PMID 38493138, 2024). "Additionally, our study demonstrated that elevated levels of respiratory immune mediators, including IL-10, IL-6, MCP-1, and MCP-3, were significantly associated with COVID-19 severity." (PMID 39633683, 2024). "Therefore, using a gene candidate approach, we aimed to analyse the impact of IL-6 variants (rs1800797 and rs1800795) on SARS-CoV-2 infection and the clinical progression of COVID-19 in a Moroccan population." (PMID 38783290, 2024). "In addition, a study showed that elevated serum IL-6 and CRP levels were closely associated with the severity of pneumonia in COVID-19 patients." (PMID 39337223, 2024). "Moreover, IL-6 and osteopontin were correlated with BMI in critical COVID-19 patients in contrast to severe COVID-19 patients." (PMID 39507250, 2024). "Taken together, our data show that IFN-γ-licensed MSCs are capable of modulating the immune response triggered by the inflammatory milieu produced by lung cells exposed to NS antigens, reducing the levels of critical cytokines in COVID-19, such as IL-10 and IL-6." (PMID 39415027, 2024). "IL-6 is an effective therapeutic target in inflammatory diseases and tocilizumab, a monoclonal antibody that blocks signaling via the IL-6 receptor (IL-6R), is used to treat patients with severe COVID-19." (PMID 39835136, 2024). "This study shows albumin, lymphocytes, platelets and ferritin as factors that may correlate with the severity of COVID-19, and with regard to pro-inflammatory cytokines, the authors found IL-6, IL-10, IL-2 and IL-17 to be elevated in severe patients." (PMID 38807995, 2024). "Phospholipase A2 (PLA2) and IL-6 are predictive markers for the severity of COVID-19." (PMID 38674024, 2024). "Hence, T-cell counts in COVID-19 were subsequently shown to be negatively correlated with IL-6, TNF-α and IL-10 blood levels, particularly in the elderly." (PMID 39896810, 2024).
COVID-19 (continued). "A combination of FER-1 and N-acetylcysteine (NAC) could reverse ferroptotic effects of IL-6 and help resolve FeRD in COVID-19 and PASC patients." (PMID 38555403, 2024). "The analysis conducted allowed us to identify specific structural features within molecules of the furosemide family that directly interact with key active sites involved in the progression of COVID-19, particularly regarding anti-inflammatory cytokine activity against IL-6 and TNF-α." (PMID 39065617, 2024). "Notably, the clinical efficacy of IL-1 inhibition (anakinra) and IL-6 inhibition (tocilizumab or sarilumab) was studied in COVID-19 patients with respiratory insufficiency and hyperinflammation." (PMID 38392902, 2024). "COVID-19 can induce cytokine storms, such as IL6, IL32, CD83, CCL2, CXCL11, the TNF family (TNFSF9 and the receptor TNFRSF9), and integrin-related genes, which exacerbates COVID-19 related myocarditis and decreases the prognosis of patients requiring ECMO treatment." (PMID 39026189, 2024). "Indeed, many studies have demonstrated that IL-6 is significantly elevated in patients with COVID-19 and is predictive of poor outcomes." (PMID 38617587, 2024). "Therefore, IL-6 inhibitors have been widely used as an effective treatment option in severe COVID-19 cases." (PMID 38694512, 2024). "Our results suggest a higher baseline IL-6 reservoir protecting against developing severe COVID-19." (PMID 39062668, 2024). "COVID-19 as a viral infection, is characterized by unique hyperinflammatory signatures across all types of immune cells, among which is the upregulation of IL-1β-, IL-6, and TNF-α-driven inflammatory responses, especially in severe cases." (PMID 38183501, 2024). "The study suggested that COVID-19 may worsen periodontal disease by increasing IL-6 production, leading to inflammation and tissue damage to the gums." (PMID 38800223, 2024). "We detected significantly higher inflammatory responses in COVID-19 positive pregnant women evident by increased IL-6 and TNF-α, which have been reported to induce the likelihood of preterm birth and can impact the development of the fetal neurological and respiratory system." (PMID 39048938, 2024). "This subsequently induces IL-6 expression, which is also promoted in COVID-19." (PMID 38674024, 2024). "Because of the imbalance in the immune system, patients with autoimmune thyroid disorders may have more severe COVID-19 than healthy individuals due to higher baseline serum concentrations of IL-6 and TNF-α." (PMID 39045269, 2024). "The biomarkers CRP, IL6, IP10, IL8, IL1RA, and suPAR showed also a good performance in identifying those participants at risk of developing severe COVID-19, defined as patients who required oxygen by non-invasive ventilation or high flow, intubation and mechanical ventilation, or who died." (PMID 39664394, 2024). "The IL-6 inhibitor, tocilizumab, has also shown some benefit in the treatment of COVID-19." (PMID 38966229, 2024). "Systemic inflammation evoked by SARS-CoV-2 is a hallmark of COVID-19, and one of the most widely used biomarkers for inflammation is an acute-phase protein CRP, which is biosynthesized in the liver in response to elevated interleukin-6 levels." (PMID 38570550, 2024). "Therefore, our study revealed that the expression of cytokines, such as IL-6 and IL-10, which have been consistently verified to be involved in the progression of COVID-19 by other studies, is up-regulated as the disease gradually became more severe." (PMID 38710800, 2024). "Based on the successful experience from COVID-19 critical cases, it is reasonably hypothesized that IL-6 is able to restore hemodynamic stability in children with febrile neutropenia who develop severe sepsis/septic shock." (PMID 38672594, 2024). "The rise in IL-6 that accompanies COVID-19 may prevent autophosphorylation and activate the phosphoinositide 3 kinase (PI3K) and protein kinase B (AKT) pathways, thereby worsening insulin resistance in diabetics." (PMID 38390960, 2024).
COVID-19 (continued). "Thirdly, although routine microbiological sampling was performed in all patients, we cannot exclude the possibility of bacterial superinfections in the COVID-19 group, which may have partially influenced IL-6 levels." (PMID 38598083, 2024). "The present study, which supports these findings, evaluated a larger, unselected collective and may thus extend the predictive value of IL-6 in detection of AKI to COVID-19 patients outside of ICU." (PMID 38336628, 2024). "However, recent findings of elevated IL-6 levels in COVID-19 patients have spurred numerous clinical trials exploring IL-6-targeted strategies." (PMID 39056754, 2024). "The cytokine triad of IL-1β, IL-6, and TNF is associated with the post-acute sequelae of COVID-19." (PMID 38932387, 2024). "Inflamed airways show high levels of IL-13 (asthma), IL-8 or IL-6 (COVID-19; cytokine storm,)." (PMID 37979051, 2024). "Niacin (B3) supplementation may also assist COVID-19 patients in reducing the inflammatory process, which is often triggered by IL-6 and is generated during the early stages of inflammatory cascade." (PMID 38390861, 2024). "In COVID-19, IL-6 plays a significant role in cytokine storms." (PMID 39281667, 2024). "Moreover, circulating IL-6 levels were significantly higher in patients with IMV-COVID compared to severe or moderate COVID-19." (PMID 39882243, 2024). "During cytokine storms in patients with COVID-19, interleukin (IL)-6 and tumor necrosis factor (TNF)-α have been used to reduce suppressive functions of T regulator cells, resulting in an increase in IL-17 and reduction in interferon (IFN)-γ expression in inflamed tissue." (PMID 39861800, 2024). "CRP, IL6 and IP10 had the most robust association with both hospitalization and severe COVID-19, with CRP having the highest discriminatory capacity with hospitalization, and IL6 for severe COVID-19." (PMID 39664394, 2024). "Elevated levels of IL-6 and TNF-α are strongly associated with COVID-19 severity." (PMID 39408907, 2024). "Additionally, the inflammatory cytokine storm induced by COVID-19, characterized by elevated levels of cytokines such as IL-6 and TNF-α, can create a tumor-friendly microenvironment." (PMID 39156288, 2024). "However, critical and severe COVID-19 patients present higher IL-6 and IL-10 plasma levels compared to moderate cases of the disease." (PMID 38474248, 2024). "For instance, genotyping of cytokine-related single-nucleotide polymorphisms (SNPs), e.g., IL-6 rs1800796, IL-10 rs1800896, TNF-α rs1800629, and IFITM3 rs12252, has shown them to underlie the differential viral virulence and severity of COVID-19." (PMID 38400050, 2024). "Furthermore, bio-ADM and IL-6 were significantly elevated in COVID-19 patients reaching the composite endpoint (each p < 0.001)." (PMID 38336628, 2024). "Furthermore, autoimmune diseases can be triggered by COVID-19 in genetically predisposed patients, following the activation of an aberrant immune response by the cytokine cascade (TNF-α, IL-6, IL-1β, IL-17, and IL-18) induced by SARS-CoV-2." (PMID 38707102, 2024). "Given that IL-6 is one of the pivotal inflammatory factors, these TCM ingredients may mitigate the cytokine storm in COVID-19, lower the risk of disease aggravation, and improve patient outcomes." (PMID 38799438, 2024). "In contrast, individuals without COVID-19 who had a moderate to severe risk of OSA exhibited a significant positive correlation with serum IL-6 (p = 0.04)." (PMID 38476500, 2024). "Since, IL-6 and Tumor necrosis factor-alpha (TNF-α) levels are the major contributors of cytokine storm syndrome in the lungs during COVID-19, we also evaluated the mRNA expression of IL-6 and Tumor necrosis factor-alpha (TNF-α) in the vaccinated vs. unvaccinated hamsters." (PMID 39911577, 2024). "High IL-6 concentration at baseline is a strong predictor for ACS development in COVID-19 patients." (PMID 39395941, 2024).
COVID-19 (continued). "Secondly, the systemic inflammatory response syndrome (SIRS) induced by COVID-19 can lead to a cytokine storm, characterized by the release of large quantities of pro-inflammatory cytokines such as interleukin-6 (IL-6), interleukin-1β (IL-1β), and tumor necrosis factor-alpha (TNF-α)." (PMID 38999316, 2024). "Interleukin-6 (IL-6), a pro-inflammatory cytokine, has been extensively studied in the context of COVID-19 due to its role in the cytokine storm syndrome, which could be linked to the pathogenesis of changed headaches through systemic inflammation." (PMID 38890625, 2024). "The explanation of these findings may refer to the presence of multiple factors, including several ncRNAs that affect the IL6 level in COVID-19 patients." (PMID 39729489, 2024). "The key enzymes required for the metabolism of various antipsychotics are blocked by IL-6 to varying degrees, and this may be a possible reason for the decline in the metabolism of various antipsychotics after COVID-19." (PMID 39077630, 2024). "Interestingly, Leisman’s study found significantly lower levels of IL-6 in severe COVID-19 patients compared to other inflammatory conditions like ARDS, sepsis, and CRS." (PMID 39063142, 2024). "In this study, we screened for c-aAb targeting IFNα, IFNβ, IFNγ, IL-1α, IL-6, IL-10, and GM-CSF in the Surviving Pneumonia Study cohort, comprising 665 patients with CAP caused by COVID-19, influenza virus, bacteria, or unknown pathogen." (PMID 39606243, 2024). "This storm involves various immune cells, like B cells, T cells, and macrophages, all releasing high levels of pro-inflammatory cytokines such as interleukin-1 (IL-1), IL-6, and tumor necrosis factor-α (TNF-α), linked to the severe lung damage observed in many COVID-19 cases." (PMID 38732328, 2024). "In the case of COVID-19, an impaired type I interferon response associated with a persistent blood virus load and an exacerbated inflammatory response driven by NF-κB, particularly by increased TNF-α and IL-6 production, were observed in a cohort of fifty COVID-19 patients." (PMID 39125989, 2024). "In WAVE III, the serum levels of IL-6 and sIL-6R continued to be significantly increased in COVID-19 patients compared to healthy controls (63.15 ± 18.5 pg/mL vs. 1.91 ± 0.89 pg/mL, p < 0.01 and 75.21 ± 14.29 ng/mL vs. 26.51 ± 8.16 ng/mL, p < 0.05, respectively)." (PMID 39063569, 2024). "Studies show that excessive production of IL-6 could lead to multi-organ failure and contribute to a severe form of COVID-19." (PMID 39335569, 2024). "Therefore, bio-ADM and IL-6 have high predictive value in COVID-19 patients at admission to the ED and thus can contribute to early risk stratification." (PMID 38336628, 2024). "Patients in the ACLF+COVID-19 group were more likely to have hepatic encephalopathy (p=0.015), lower platelet count (p=0.016) and elevated IL-6 level (p=0.026), and higher MELD-Na score (p=0.041) one week after admission, but without a significant increase in 28-day mortality rate (p=0.16)." (PMID 39867341, 2024). "Moreover, as a pathogen, COVID-19 can trigger a cytokine release syndrome, characterized by elevated levels of inflammatory cytokines, including IL-1β, interleukin 1 (IL-6), interleukin 12 (IL-12), IFN-γ, and TNF-α." (PMID 38287388, 2024). "We also observed patterns of chronic inflammation downregulation in COVID-19 (+) tissues, specifically the downregulation of IL-6, a key gene in promoting chronic inflammation by recruiting monocytic lineages to replace first responder polymorphonuclear neutrophils." (PMID 38932146, 2024). "Furthermore, the effect of the time interval after acute COVID-19 was also significant for both IL-6 (F = 9.4, p = 0.003) and IL-17 concentrations (F = 6.12, p = 0.016)." (PMID 38424126, 2024).